CD4 (CD4 molecule)
Diseases named in the same sentence as CD4 in open-access papers (continued):
Sharing a sentence is not in itself a finding about the gene and the disease.
pulmonary TB (continued). "We demonstrated significantly high levels of TNF-α, IFN-γ, and VEGF and an increased CD4+/CD8+ ratio of T lymphocytes in BALF from TPE patients without active pulmonary tuberculosis." (PMID 22889060, 2012). "At TB diagnosis, 65% of TB patients had a CD4+ count <100 cells/μL, 26% had a previous history of TB, and 43% had extra-pulmonary TB (with or without co-existent pulmonary TB)." (PMID 22719843, 2012). "The concentrations of interferon-γ (IFN-γ), tumor necrosis factor-α (TNF-α), vascular endothelial growth factor (VEGF), and the CD4+/CD8+ ratio of T-lymphocytes were significantly higher in TPE patients without pulmonary tuberculosis than in the controls." (PMID 22889060, 2012). "In the remaining 208 patients with CD4 count, 195 (94%) were eligible for ART as per the NACO guidelines (181 having CD4 count ≤350/mm3 and 14 with >350/mm3 but having Extra pulmonary TB), but of the eligible, only 157 patients received ART (not on table)." (PMID 21814542, 2011). "It was noted that in the new-onset patients with pulmonary tuberculosis, thick-walled bacilli were negatively correlated with CD4+/CD8+ and CD14+CD16+ and are positively correlated with CD14+CD16-; at the genus level, Enterococcus faecalis was positively correlated with CD4+/CD8+ and CD4+43." (PMID 35383237, 2022). "In TB patients, a slightly increased expression of granzyme-B was shown in CD8+ and CD4+ T cells, but not NK cells, which is contradict to the recent findings that active pulmonary TB patients downregulated granzyme-B expression in CD8+ T cells in comparison with latent TB infection." (PMID 32823923, 2020). "This prospective cohort study, composed of participants within a larger phase 3 open-label randomized controlled clinical trial, measured the impact of TB treatment on immune activation in persons with non-advanced HIV infection (CD4>350 cells/mm3) and pulmonary TB." (PMID 20179751, 2010). "Decreased Th-1 responses could favor reactivation of latent TB infection (LTBI), although the helminth species-specific effect on IFN-γ+CD4+ T cells and the link to TB disease severity in patients with active pulmonary TB (PTB) have not been fully investigated." (PMID 36662839, 2023). "Moreover, the increased IFN-γ production from PBMCs of pulmonary TB patients upon stimulation with either early secretory antigenic target of 6 kDa (ESAT6) or culture filtrated protein 10 (CFP10), and the high expression of IFN-γ by CD4+ T cells and CD8+ T cells have been recently demonstrated." (PMID 32823923, 2020). "Splenic infection of the diet-D fed animals might have accelerated the maturation of double positive T-cells inclined towards CD4+63 rather than CD8+ and could explain increased CD4+/CD8+ T cells ratio, something also found to be correlated with pulmonary tuberculosis in leptin-deficient mice." (PMID 29116252, 2017). "The expression of PD-1 and PD-L1 on CD4+ T cells, CD8+ T cells, and CD14+ monocytes in PBMCs from pulmonary TB patients, LTBI cases, and non-TB, non-LTBI individuals was measured by flow cytometry." (PMID 35163542, 2022). "The aim of this study was to compare the blood monocyte, neutrophil, CD4+ and CD8+ T-lymphocyte counts, and the CD4:CD8 ratio among three categories of people with pulmonary TB: never smokers, past smokers, and current smokers." (PMID 36123871, 2022). "A study of 36 subjects examining the cytokine responses of CD4+ T-cells in BAL demonstrated strong IFN-γ and TNF-α responses among patients with pulmonary TB as opposed to healthy control subjects and in lung compared to peripheral blood." (PMID 24376464, 2013). "The recommendation for HIV positive pregnant women with pulmonary TB classified as WHO clinical stage 111 and 1V are eligible for ARV therapy irrespective of CD4 lymphocyte counts." (PMID 21541068, 2011). "Of the 419 pulmonary TB patients not already on ART, 352 (84%) had available CD4 information, among whom 291 (83%) had a CD4 count <350 cells/mm3 and were ART eligible." (PMID 21931674, 2011).
pulmonary TB (continued). "While the LF-LAM test (Lateral Flow Urine Li-poarabinomannan) is indicated as an additional test in HIV positive children, presenting signs and symptoms of pulmonary tuberculosis and in those who are HIV positive without symptoms with a CD4 cell count < 100/mm3." (PMID 37512894, 2023). "Though BCG-vaccination induces CD4+ and CD8+ effector T-cell responses in newborns and protects them from disseminated forms of disease, it does not induce consistent protection against pulmonary TB, especially in adults." (PMID 26029205, 2015).
latent infection (208 papers, 2007 to 2025). "On the contrary, exogenous expression of wild-type PRMT2, rather than a methylase-deficient variant, markedly increases the latent infection of primary CD4+ T cells by HIV-1GKO viruses." (PMID 37949879, 2023). "CD27 and CD26 were among the markers which best discriminated fast and slow responders, consistently with prior studies associating CD27 and CCR4 expression in Mtb-specific CD4+ T-cells with active TB compared to latent infection." (PMID 35392094, 2022). "We demonstrate that tonsillar memory CD4+ T cells expressing CD127 are indeed biased to undergo latent infection, and further characterize host features associated with suppression of viral gene expression in these cells." (PMID 32353080, 2020). "HIV-infected individuals with low CD4+ T cell count coinfected with T. gondii are at higher risk of reactivating the latent infection." (PMID 25431660, 2014). "Efforts to elucidate differences between the immune response profile of individuals with latent infection and patients with progressive disease suggest that latency is associated with maintenance of subsets of CD4 T cells." (PMID 21197095, 2011). "Similarly, T. gondii latent infection caused an increase in conventional CD4+ T cells producing IFN-γ upon PMA/ionomycin restimulation, with the most prominent increase observed among the resident CD49a-positive subset." (PMID 40300021, 2025). "Besides, in young individuals, CMV latent infection associates with the expansion of CD57+CD161−CD300a+CD4+, CD57−CD161−CD300a+CD4+, CD57+CD161−CD300a+CD8+, CD57−CD161−CD300a+CD8+, CD57+CD161−CD300a+NKT-like, and CD57+CD161−CD300a+DN T-cells." (PMID 28626460, 2017). "In addition, CD4+ T cells typically producing more than one cytokine are thought to be associated with a protective immune response and indeed, these multi-functional Th1 cells have been shown to be enhanced in latent infection compared to active disease." (PMID 28558065, 2017). "Studying populations with elevated risk of TB infection and/or reactivation, such as HIV-infected individuals, may help shed light on the mechanisms involved in the heightened risk of TB disease in HIV-infected individuals with latent infection, even before CD4 depletion is profound." (PMID 27865393, 2016). "At different time points after infection, CD4+ T cells, where MDV primarily establishes latent infection, were sorted from the spleen, and the purity of isolated CD4+ T cells was examined by flow cytometry." (PMID 39840986, 2025). "HIV is a retrovirus that can target CD4+ lymphocytes to establish both productive and latent infections." (PMID 41207052, 2025). "Their activation in their resident tissue is likely mediated by a tripartite interaction with CD4+ T cells, which are present during latent infection, and DC." (PMID 40431612, 2025). "Using fate mapping and murine genetic tools, we demonstrate that alternative activation of monocyte-derived myeloid cells by CD4+ T helper 2 cells antagonizes pulmonary fungal clearance during latent infection." (PMID 40568097, 2025). "HIV infection compromises immune function primarily by depleting CD4+ T-cell counts, which are pivotal in controlling Mycobacterium tuberculosis in latent infections." (PMID 40238330, 2025). "Marek’s disease virus (MDV), a highly contagious and oncogenic avian alphaherpesvirus, establishes a latent infection primarily in CD4+ T cells." (PMID 39840986, 2025). "MDV establishes a latent infection in CD4+ T-cells, which defines the latency phase and immune evasion between 7- and 10-dpi." (PMID 40733625, 2025). "To further test if Δgcs1 infection was a good mimic of latent infection controlled by adaptive immunity, we administered anti-CD4 antibodies to deplete CD4+ T helper cells starting from the peak of infection, 35 dpi." (PMID 40568097, 2025). "At approximately 7 dpi (second phase), MDV establishes a latent infection, mostly in CD4+ T cells, by integrating its genome into host telomeres." (PMID 39840986, 2025).
latent infection (continued). "To elucidate these mechanisms, we developed in vivoand in vitro models through which our findings revealed that PEDVestablishes latent infection in CD4+ T cells and then promotes intestinalhoming of CD4+ T cells by modulating integrin expression." (PMID 40094365, 2025). "Further investigations revealed that PEDV predominantly infects CD4+T-cell subsets, establishing latent infections within them." (PMID 40094365, 2025). "Thisstudy elucidates the cellular mechanisms behind the process, demonstratinghow PEDV is internalized by CD4+ T cells after being transferredby dendritic cells, where it establishes a latent infection." (PMID 40094365, 2025). "The observed significant increase of CD8+ T cells during acute CMV infection and a relativedrp predominance of CD4+ T cells in latent infection revealed host responses similar to those in human." (PMID 41473769, 2025). "We observed that LPR and GLD mice showed significantly lower numbers of CD4+ T cells during both early and latent infection compared to wild-type mice (p ≤ 0.001)." (PMID 41439958, 2025). "HIV infection remains incurable, with the primary barrier to eradication being the persistence of latent infection, particularly in memory CD4+ T cells." (PMID 40574839, 2025). "Differential expression of Mtb-specific CD4+ T cell activation markers distinguishes EPTB from latent infection." (PMID 38384272, 2024). "Previous studies have demonstrated that HIV-mediated signaling through CXCR4 is critical for latent infection of blood resting CD4+ T cells." (PMID 39146384, 2024). "The TIQ-15-mediated inhibition of SDF-1α-induced cofilin activation are consistent with a demonstrated role of early actin dynamics in HIV latent infection of blood resting CD4 T cells." (PMID 39146384, 2024). "It has been demonstrated that antigen-specific expression of TNFa in theabsence of IFNg on CD4+ T cells in Mtb-infected patientsstrongly correlates with the potential to develop active TB, while the opposite phenotypeis supportive of latent infection." (PMID 39257997, 2024). "It was found by flow cytometry that the specific CD4+T cells of dominant TNF-α+Mtb were different in latent infection and active infection." (PMID 37901241, 2023). "The difference of GFP expressions in PMA/I stimulated CD4 + T cells versus unstimulated CD4 + T cells represented latent infection." (PMID 37202790, 2023). "For instance, CCL-2 was recently shown to mediate early seeding of the HIV reservoir by recruiting a unique subset of CCR2/5+ CD4+ T-cells which become infected and form a significant reservoir for latent infection." (PMID 36992409, 2023). "Not only did IEC induce latent infection in activated CD4 + T cells, but they also substantially increased the level of productive infection in activated CD4 + T cells." (PMID 37202790, 2023). "Some found infecting activated CD4 + T cells after their peak of activation generated higher levels of latent infection." (PMID 37202790, 2023). "In activated CD4 + T cells, endothelial cells enabled the formation of latent infection in addition to the increase of productive infection." (PMID 37202790, 2023). "Another study found that when infected ex vivo, CD4 + T cells isolated from splenic and tonsillar lymphoid tissues had significantly higher latent infection rates when compared to purified CD4 + T cells isolated from peripheral blood." (PMID 37202790, 2023). "To investigate latent infection, we cultured resting CD4 + T cells with IEC for one day and infected them with the GFP reporter virus." (PMID 37202790, 2023). "Others have shown that chemokines and cell-cell interactions can promote HIV infection of resting CD4 + T cells, including latent infections." (PMID 37202790, 2023). "While resting CD4 + T cells form low levels of latent infection, upon IEC stimulation, the levels of latent infection were substantially increased." (PMID 37202790, 2023).
latent infection (continued). "CD4+ T cells are the widely studied signature for virus persistence and latent infection with the ability to sustain viral infection with a half-life of up to 44 months." (PMID 37513726, 2023). "The factors that are known to control the latent infection include macrophage, CD4 T cells, CD 8 T cells, and gamma interferon (IFN-γ)." (PMID 35746572, 2022). "Potentially, CMV-seropositive donors do not elicit as robust a response due to CMV-mediated downregulation of antigen presentation to CD4+ T cells during latent infection." (PMID 35192547, 2022). "Like HIV-1, HIV-2 is capable of establishing latent infection in CD4+ T cells, thereby allowing the virus to evade viral cytopathic effects and detection by the immune system." (PMID 35476802, 2022). "We show that CD4 T cells, exposed to virus prior to induction of cell activation, are more likely to develop stable latent infection." (PMID 35895672, 2022). "Such minimally activated CD4 T cells would then be expected to preferentially survive with persistent or latent infection." (PMID 35895672, 2022). "IFNα from plasmacytoid DCs inhibited the establishment of latent infection in CD4 + T cells in vitro." (PMID 35804422, 2022). "The binding of interferon-γ-induced protein (IP) -10 to C-X-C chemokine receptor 3 (CXCR3) has also been reported to enhance latent infection of resting CD4+T cells against HIV." (PMID 35967854, 2022). "It has also been shown that HIV preferentially establishes a latent infection in a specific CD4+ T cell population identified as an effector of memory transitioning population and that HIV silencing correlates with downregulation of NF-κB." (PMID 35499323, 2022). "The major barrier to curing HIV-1 and HIV-2 is the ability of these viruses to establish a latent infection in some CD4+ T-cells and possibly other cells." (PMID 35476802, 2022). "Unfortunately, this is a common limitation of the vast majority of available current in vitro models of latent infection in CD4 T cells." (PMID 35895672, 2022). "In contrast to total infection, the differences in latent infection were less pronounced in the different CD4+ T cell subsets." (PMID 35499323, 2022). "have also demonstrated that the establishment of HIV latent infection in CD4+ T cells was promoted by CCL19/21-mediated increases of actin dynamics via the cofilin pathway." (PMID 34447368, 2021). "We determined the phenotype, function and transcriptional correlates of PD-1 expression on cytomegalovirus-specific CD4+ T cells during latent infection." (PMID 33662046, 2021). "HIVGKO infection consistently established latent infection (GFP-mKO2+) in purified CD4+ T cells from different tonsil donors." (PMID 34531866, 2021). "As reported in CD34+ latent infection, the CD14+ latency-associated secretome also suppressed the anti-viral activity of stimulated CD4+ T cells." (PMID 33912186, 2021). "Previously, we have shown that experimental latent infection of CD34+ progenitor cells alters the cellular secretome to induce migration of CD4+ T cells and subsequent suppression of their effector function." (PMID 33912186, 2021). "Cells expressing the Tbet transcription factor were the predominant activated CD4 T-cell subset in the lungs during the latent infection." (PMID 35186781, 2021). "Given the demonstrated ability of CD2 to activate the cofilin pathway, we investigated potential impacts of CD2 signaling on HIV latent infection of resting CD4 T cells." (PMID 34765923, 2021). "For example, HIV-1 binding to the chemokine coreceptor CXCR4 or CCR5 has been shown to trigger G-protein signaling critical for HIV latent infection of blood resting CD4 T cells." (PMID 34765923, 2021). "IP-10 has been found to activate the cofilin pathway and promote HIV latent infection of resting memory CD4 T cells, likely by a similar mechanism through synergizing with HIV-mediated CXCR4 signaling." (PMID 34765923, 2021).